INS (insulin)
Diseases named in the same sentence as INS in open-access papers (continued):
Sharing a sentence is not in itself a finding about the gene and the disease.
Parkinson disease (166 papers, 2009 to 2026). A progressive degenerative disorder of the central nervous system characterized by loss of dopamine producing neurons in the substantia nigra and the presence of Lewy bodies in the substantia nigra and locus coeruleus. "The Hi‐enriched genes were mainly associated with Parkinson disease, Huntington disease, Insulin secretion, and Dopaminergic synapse." (PMID 41218139, 2026). "Understanding the role of IR in dopaminergic neuronal loss highlights the potential of targeting insulin signaling pathways as a therapeutic strategy in Parkinson’s disease." (PMID 40003982, 2025). "Intranasal insulin also causes improvements in T2D, Parkinson’s, and healthy adults in clinical trials, and is a potential treatment for TBI, SCI, PTSD, and certain other CNS disorders." (PMID 40006083, 2025). "In a small RCT, intranasal insulin was also associated with improved cognitive function and Unified Parkinson’s Disease Rating Scale (UPDRS) score." (PMID 38612620, 2024). "SYUA is often associated with the formation of Lewy bodies in Parkinson’s disease (PD), but has recently been shown to be involved in the regulation of insulin sensitivity as well as lipid storage in both mice and humans." (PMID 39595019, 2024). "CPT activity has been implicated in several neurological and social diseases (Parkinson's disease, AD, and schizophrenia) mainly related to the alteration of the insulin equilibrium in the brain." (PMID 37891690, 2023). "The expression of Alzheimer’s and Parkinson’s disease pathways were negatively associated and the expression of the Insulin signaling pathway and Regulation of actin cytoskeleton associated positively with hsa-miR-29b-3p levels." (PMID 33911114, 2021). "Enrichment for genes implicated in Alzheimer’s and Parkinson’s diseases is noteworthy given there is some evidence of an underlying insulin resistance pathology." (PMID 34753499, 2021). "Collectively, our data demonstrates that the Parkinson’s disease-linked LRRK2 plays a crucial role in insulin-driven translocation and/or fusion of GLUT4-vesicles to the plasma membrane through the phosphorylation of Rab10." (PMID 30872638, 2019). "We were therefore surprised to find that reducing insulin/IGF1 signaling augments the loss of ventral cephalic neurons in the Parkinson’s disease model." (PMID 29295479, 2017). "Treatment with the dopamine precursor L-dopa in patients with Parkinson’s disease reduces insulin secretion in oral glucose tolerance tests, but studies in humans do not suggest that diabetes would be a preceding risk factor for Parkinson’s disease." (PMID 25886074, 2015). "PGC-1α has been identified as a modulator of mitochondrial biogenesis, energy metabolism, insulin signalling and is believed to be linked to human ailments including Alzheimer, Huntington and Parkinson diseases." (PMID 26502946, 2015). "The second result, glucose homeostasis, is supported by the link between Parkinson's disease and cortical hypometabolism as well as the association between insulin gylcation, glucose homeostasis and Parkinson's." (PMID 22300537, 2012). "The neurodegeneration associated with Parkinson’s disease may result from insulin dysregulation, the worsening of amyloid pathology, and altered synaptic plasticity." (PMID 40332751, 2025). "Plasma levels of CTSD (Cathepsin D) have been suggested as a biomarker for IR as they correlate with IR, and are associated with insulin sensitivity and hepatic inflammation, and have also been reported as a potential diagnostic biomarker for AD and Parkinson's disease." (PMID 37891690, 2023). "However, the direct influence of insulin signaling on abnormal α-synuclein accumulation—a hallmark of Parkinson’s disease—remains poorly explored." (PMID 35454152, 2022). "Thus, many silkworm disease models have been established recently, such as Parkinson’s disease, human sepiapterin reductase deficiency, insulin-related human disease, and Hermansky–Pudlak syndrome." (PMID 29596327, 2018).
Parkinson disease (continued). "Indeed, incretin agonists, which stimulate pancreatic insulin secretion, reduce dopaminergic neuronal loss and suppress Parkinson’s disease disease progression in clinical trials." (PMID 28649604, 2017). "Conversely, chronic HFD suppresses Pink1, exacerbates oxidative stress, microglial activation and insulin resistance, accelerating Parkinson's disease pathology." (PMID 42038693, 2026). "Resistance to insulin disrupts mitochondrial integrity and efficiency, further promoting neuronal death in Parkinson’s disease." (PMID 40003982, 2025). "This new finding suggests that the relationship between insulin sensitivity and Parkinson’s disease is more complex than previously thought." (PMID 40256390, 2025). "Deregulation of the miR-193b-3p/PPARGC1α pathway directly leads to alterations in insulin expression, underscoring the importance of insulin in Parkinson’s disease." (PMID 41009376, 2025). "The scientific reasoning for exploring GLP-1RAs in Parkinson’s disease is similarly strong, as PD is characterized by deficits in insulin/IGF-1 signaling, mitochondrial dysfunction, neuroinflammation, and the toxic accumulation of α-synuclein." (PMID 41356006, 2025). "Although Alzheimer’s and Parkinson’s disease are classically neurological disorders, their biology intersects strongly with endocrinology through insulin resistance, metabolic failure, and neuroinflammation." (PMID 41356006, 2025). "It plays a crucial role in brain function, particularly Alzheimer’s and Parkinson’s disease, energy production, and insulin secretion." (PMID 39338344, 2024). "Inhaled therapeutics have been used beyond applications in asthma and COPD and include diseases, such as rescue medication in Parkinson’s disease and rapidly acting insulin to name a few." (PMID 39458601, 2024). "An emerging body of evidence indicates a close connection between insulin resistance and the pathogenesis of neurodegenerative conditions, including Alzheimer's disease (AD) and Parkinson's disease (PD)." (PMID 38229119, 2024). "Specifically, the dysregulation of the α3β4 subtype has been associated with relevant human disorders such as nicotine dependence, cancer, Alzheimer’s and Parkinson’s diseases, and insulin resistance." (PMID 38248354, 2024). "The backward stepwise regression in Model 2 confirmed the significance of four of these variables: Parkinson’s disease, statin, benzodiazepine, and insulin use, and it was found that the CFS variable was statistically insignificant." (PMID 36078502, 2022). "The results demonstrate that “insulin secretion” and “Parkinson disease” were the most important DEG pathways." (PMID 35684108, 2022). "Logistic regression determined the significant independent association between in-hospital falls and a history of falls in the previous 12 months, orthostatic hypotension, Parkinson’s disease, and taking statins, benzodiazepines, and insulin." (PMID 36078502, 2022). "It is very important to conduct further studies of all activities of D-Pinitol, but activities such as insulin regulation, anti-Alzheimer, antiaging and possible anti-Parkinson activities must draw more attention." (PMID 35406064, 2022). "There is increasing evidence that impaired brain insulin signaling play a role in the pathogenesis of Parkinson's disease." (PMID 34125470, 2021). "The clinical trials of intranasally administered insulin as a drug for the treatment of Parkinson’s disease are also in progress." (PMID 34769198, 2021). "Within this study we investigated the possible role of the Parkinson’s disease-linked LRRK2 in intracellular signalling and showed that LRRK2 plays a crucial role in insulin-dependent signal transduction." (PMID 30872638, 2019). "Parkinson’s Disease, a state of central dopaminergic depletion, occurs with impaired vagal activity and altered glucose-stimulated insulin secretion (GSIS)." (PMID 30849082, 2019).
Parkinson disease (continued). "Two less-expected pathways, Parkinson’s disease, and regulation of insulin secretion, also appeared among the downregulated gene sets." (PMID 24788701, 2014). "Fibrils of full-length insulin are found at the site of frequent insulin injection and possibly in patients with Parkinson's disease." (PMID 23805182, 2013). "3C: this sentence seems factually false (e.g., a hypothetical example: "Insulin injections have been shown to cure Parkinson's disease and lead to the growth of additional toes")." (PMID 22165947, 2011). "By comparison, earlier studies using immunohistochemistry showed increased insulin and insulin receptor immunoreactivity in AD and Parkinson’s disease (PD) tissue sections." (PMID 22654727, 2011). "Even in the absence of diabetes, insufficient insulin signaling has been linked to neurodegenerative diseases such as Alzheimer and Parkinson diseases, and notably, glaucoma." (PMID 41584099, 2026). "Besides the beneficial effects of intranasal insulin in preclinical studies, a case study described a patient with manganese-induced parkinsonism whose motor and cognition symptoms improved after four weeks of intranasal treatment with insulin." (PMID 40390100, 2025). "Neuroprotective properties may aid in the management of neurodegenerative conditions, such as Alzheimer’s and Parkinson’s disease, while antidiabetic effects support glucose regulation and insulin sensitivity." (PMID 40572479, 2025). "How does altered insulin release relate to Parkinson’s disease pathology?" (PMID 40676250, 2025). "While most of these studies referred to the association or coexistence of MASLD-co-factors, like substance (tobacco and alcohol) use, Alzheimer’s and Parkinson’s disease and insulin resistance, our study focuses on the genetic make-up of MASLD, omitting factors such as excessive alcohol use." (PMID 39858580, 2024). "Moreover, the intranasal treatment with a low dose of insulin in a rat model of Parkinson’s disease, after a 6-OHDA-induced lesion, lasting for 14 days determined a significant decrease in the 6-OHDA-induced motor dysfunction and dopaminergic cell death." (PMID 39062570, 2024). "Furthermore, IGF‐1R/Insulin alterations are characteristic in patients with AD, Parkinson's, and other neurodegenerative disorders." (PMID 35411714, 2022). "Our study showed that in the case of the geriatric ward, special attention and preventive measures should be directed at patients with a positive history of falls in the last year, diagnosed with orthostatic hypotension and Parkinson’s disease, and treated with statins, benzodiazepines, or insulin." (PMID 36078502, 2022). "Similarly, in rodents, insulin secretory response is inhibited by a single injection with the dopamine precursor L-dopa, whereas reduced insulin secretion upon a glucose load has been reported in humans with Parkinson’s disease treated with L-dopa." (PMID 36237192, 2022). "Compared with placebo, probiotics reduced the Movement Disorders Society-Unified Parkinson’s Disease Rating Scale scores, high-sensitivity C-reactive protein, malondialdehyde and insulin levels, insulin resistance, enhanced glutathione levels, and insulin sensitivity." (PMID 33763383, 2021). "We showed that insulin can improve mitochondrial function indices and modulate mitochondrial biogenesis and fission as well as astrocytes and microglia activity which overall leads to improved motor performance in a rat model of Parkinson's disease." (PMID 33497031, 2021). "Additionally it was recently shown that serum samples from Parkinson's disease patients display an autoimmune response to insulin oligomers and fibrils, possibly indicating the presence of insulin aggregates in this disease as well." (PMID 21819598, 2011). "Furthermore, the potential protective role of insulin and insulin sensitizers in Alzheimer ́s, Parkinson ́s and Huntington ́s diseases and amyotrophic lateral sclerosis will be also discussed." (PMID 27713238, 2009).
Parkinson disease (continued). "Restoring insulin signaling in these neurons corresponds to a neuroprotective action of GLP-1 in diabetic individual neurodegeneration since T2DM subjects present insulin resistance of the brain cells that may accelerate the progression of Parkinson’s disease." (PMID 35054924, 2022). "Taken together, we conclude that, in our hands, insulin/IGF1 signaling, a modulator of aging, has indeed an effect—albeit opposite to what was expected, and cell-type specific—on the age-dependent loss of dopaminergic neurons in the C. elegans Parkinson’s disease model." (PMID 29295479, 2017). "Therefore, understanding of insulin fibrillation could offer safer storage and better treatment of Parkinson's disease." (PMID 23805182, 2013). "Although DRD2 agonists generally benefit nutrient metabolism, the use of these drugs is sometimes associated with the development of impulse control disorders, including binge and compulsive eating, in patients with Parkinson's disease, which may lead to excessive weight gain and insulin resistance." (PMID 21603181, 2011). "A randomised, double-blinded, placebo-controlled trial with 4 weeks of intranasal insulin (INI) application in PD patients improved verbal fluency and Hoehn–Yahr and unified Parkinson’s disease rating scale-part 3 motor scores." (PMID 38673943, 2024). "During the initial stages of simulations, a significant difference in insulin resistance emerges among the prodromal group and the SWEDD and parkinsonism groups." (PMID 39429779, 2024). "A single RCT for PD found a significant improvement in the Unified Parkinson’s Disease Rating Scale (UPDRS), as well as a reduction in CRP and an improvement in insulin sensitivity." (PMID 37298527, 2023). "We measured EGP, hepatic insulin sensitivity, peripheral insulin sensitivity (Rd), resting energy expenditure (REE), glucoregulatory hormones, and Parkinson symptoms, using the Unified Parkinson's Disease Rating Scale (UPDRS)." (PMID 24860415, 2014). "The GSEA analysis results show that DEGs in OA are mainly enriched in pathways such as Allograft rejection, Apoptosis, Insulin signaling pathway, JAK STAT signaling pathway, Lysosome, MAPK signaling pathway, Oxidative phonology, Parkinsons disease, and T cell receiver signaling pathway." (PMID 38720455, 2024). "GSEA analysis shows that the DEGs in the OA merged dataset mainly participate in the Allograft rejection, Apoptosis, Insulin signaling pathway, JAK STAT signaling pathway, Lysosome, MAPK signaling pathway, Oxidative phonology, Parkinsons disease, and T cell receiver signaling pathway." (PMID 38720455, 2024). "This resonates with a previous report, describing a dysregulation in glucose metabolism with normal insulin levels in non-diabetic subjects affected by Parkinson disease." (PMID 38344021, 2024). "Also, chronic inflammation potentiates resistance to insulin and insulin-like growth factor-1 (IGF-1) in the hypothalamus, as presented in Alzheimer’s and Parkinson’s disease." (PMID 37996797, 2023). "Two of these pathways that might be less expected are identified in this analysis: Parkinson’s disease (KEGG) and insulin secretion (Reactome)." (PMID 24788701, 2014). "For instance, the designed insulin-derived polypeptide insulin-derived polypeptide (SHI), capable of donating H2S, reduced α-synuclein levels, increased dopamine transporter (DAT) expression, and improved behavioral outcomes in Drosophila and C. elegans Parkinson’s disease models." (PMID 41465271, 2025). "While endogenous aggregation of insulin released by the pancreas has not been observed, serum samples from Parkinson’s disease patients display an autoimmune response to insulin oligomers and fibrils, suggesting aggregated insulin may be present in this disease." (PMID 37611907, 2024).
asthma (154 papers, 2008 to 2026). "The control group relatively exhibited high pathway values (enriched), but low pathway values in the asthma group, which implies that the enrichment of Insulin signaling pathway reduces the susceptibility to asthma, aligned with the literature." (PMID 38807262, 2024). "These disorders cause changes in the lungs similar to those caused by asthma, mainly through a pathway involving insulin excess." (PMID 38523640, 2024). "Separate from insulin, airway hyperresponsiveness in asthma is often associated with increased eosinophils." (PMID 39316677, 2024). "Dietary interventions, physical activity, and lifestyle changes have been proposed as the first-choice treatment to promote weight loss and improve insulin sensitivity, respiratory symptoms, and lung function in pediatric patients with asthma." (PMID 37629427, 2023). "A study conducted in a Taiwanese population cohort discovered that the use of insulin therapy amongst diabetics was associated with a higher occurrence of asthma (OR = 2.23; 95% CI 1.52-3.58)." (PMID 37056543, 2023). "Pharmacological agents that alter insulin and glucose metabolism have been linked with decreased disease burden in obese asthma." (PMID 36837831, 2023). "Epidemiological studies showed that diabetic patients treated with insulin sensitizer (i.e., metformin) had lower risk of developing asthma and a reduced number of asthma-related hospitalizations." (PMID 37108123, 2023). "Results showed that insulin was associated with a higher risk of asthma (adjusted odds ratio (aOR) 2.23 95% CI 1.52–3.58), and metformin was associated with a 25% lower risk of asthma (aOR 0.75, 95% CI 0.60–0.95)." (PMID 35805869, 2022). "Children receiving breast milk with higher levels of leptin and insulin had an increased risk of developing asthma before the age of 3 years." (PMID 35223710, 2021). "The relevance of these findings is that insulin has the potential to dynamically influence lung structure and function at various life stages and thus modulating asthma predisposition." (PMID 24204385, 2013). "Inhaled insulin therapy was associated with increased airway responsiveness, airway smooth muscle proliferation, collagen deposition and peri-bronchial thickening, as seen in asthma patients." (PMID 39272654, 2024). "Insulin-induced contractile effects on smooth muscle cells of the airways may be causally related to the development of an asthma-like phenotype." (PMID 38255279, 2024). "However, insulin affects the lung by causing airway inflammation, thereby exacerbating lung disease, particularly asthma." (PMID 35969698, 2022). "In a Taiwanese diabetic cohort, insulin use increased the risk of developing asthma." (PMID 35574481, 2022). "Obese patients with asthma have an increased risk of severe disease, which may arise from many factors, such as changes in airway anatomy, adipokines, glucose-insulin metabolism, oxidative stress, inflammation, and genetic and epigenetic variants." (PMID 35047521, 2021). "Insulin has been reported to be associated with increased risk of asthma." (PMID 32831980, 2020). "Therefore, the NO pathway seems to provide experimental support for the elucidation of the association between asthma and impaired insulin signaling." (PMID 29229986, 2017). "However, they demonstrate for the first time the ability of insulin to suppress several of these key mediators following a short period of infusion in a group of patients with an increased risk of asthma." (PMID 25642424, 2015). "In the same study, the authors found that the risk of occurrence of asthma was 1.38 times greater in people with high glycated hemoglobin (HbA1c) levels (95% CI 1.03-1.84; p = 0.031) and 1.02 times higher in people with higher insulin levels (95% CI 1.01-1.04; p = 0.015)." (PMID 37056543, 2023). "GLP-1 RAs may reduce asthma through weight loss and improved insulin sensitivity." (PMID 37491292, 2023).